LINC01564 (long independently transcribed non-coding RNA 1564)
Synonyms: TCONS_00011314; RAMS11; XLOC_005327
Gene: Long non-coding RNA gene on chromosome 6 (53,614,863 to 53,707,024, forward strand). Ensembl gene ENSG00000235899.
Diseases named in the same sentence as LINC01564 in open-access papers:
LINC01564 is named in the same sentence as 20 diseases in open-access papers, as found by Europe PMC text mining. Sharing a sentence is not in itself a finding about the gene and the disease. The quoted sentences say what the papers report.
hepatocellular carcinoma (3 papers, 2021 to 2023). A malignant tumor that arises from hepatocytes. "Meanwhile, linc01564 can promote hepatocellular carcinoma cell proliferation (HCC) survival under glucose deprivation condition by regulating PHGDH expression in mRNA and protein levels." (PMID 37127605, 2023). "The aim of this study is to detect if there is an association between expression of some long non coding RNAS (LNCRNAs) as (RAMS11, LINC01564), CBX4, and TOP2A and clinical; pathological characteristic of hepatocellular carcinoma in Egyptian patients." (PMID 36672564, 2022).
chronic hepatitis C (1 paper, 2022). "ROC curve analysis reveals the power of the relative expression levels of LINC01564, RAMS11, CBX4 and TOP2A in discriminating HCC patients from HCV group, suggesting the possible role of these molecular non-invasive markers in early diagnosis of HCC in chronic hepatitis C cases." (PMID 36672564, 2022).
gallstones (1 paper, 2024). Solid crystalline precipitates in the biliary tract, usually formed in the gallbladder, resulting in the condition of cholelithiasis. "The results indicated that AC004692.4, HECW1-IT1, SFRP4, and COMP were significantly higher expressed in gallstone samples, whereas LINC01564, SLC26A3, RP1-27K12.2, and GSTA2 were markedly lower expressed in gallstone samples compared to control samples." (PMID 38808330, 2024). "Furthermore, using RT-qPCR, we observed significant upregulation of AC004692.4, HECW1-IT1, SFRP4, and COMP, while LINC01564, SLC26A3, RP1-27K12.2, and GSTA2 exhibited marked downregulation in gallstone samples." (PMID 38808330, 2024).
infectious diarrhea (1 paper, 2024). "Furthermore, the downregulation of LINC01564 has been associated with genomic instability and metabolic adaptation in liver cancer, while SLC26A3 has been linked to inflammatory bowel disease and infectious diarrhea." (PMID 38808330, 2024).
cancer (5 papers, 2020 to 2022). A tumor composed of atypical neoplastic, often pleomorphic cells that invade other tissues. "LINC01564 has been shown to be associated with a variety of cancers." (PMID 35562740, 2022). "However, silencing of LINC01564 significantly reversed the oncogenic roles of POU2F1 in GC in vitro and in vivo, which supported that the cancer-promoting effects of POU2F1 was associated with LINC01564." (PMID 35562740, 2022). "Our study in vitro confirmed that the cancer-promoting effects of POU2F1 is dependant on LINC01564." (PMID 35562740, 2022). "A variety of cancers have been associated with long Intergenic Non-Protein Coding RNA 1564 (LINC01564) that is closely related to glutamate-cysteine ligase catalytic subunit." (PMID 36672564, 2022). "LINC01564 knockdown abolished the cancer promoting effects conferred by overexpressed POU2F1." (PMID 35562740, 2022). "It was found that 5 lncRNAs (CATIP-AS2, TTC3-AS1, LINC01993, LINC01564, and LINC02015) were upregulated in various types of cancers including GC." (PMID 34257651, 2021).
tumor (4 papers, 2020 to 2022). "As indicated by PCR assay, POU2F1 overexpression was associated with increased LINC01564 in GC tumor." (PMID 35562740, 2022). "HE staining showed that the tumors formed in the POU2F1 (OE) group were substantially larger than those in the control group, while LINC01564 knockdown suppressed the growth of tumor with POU2F1 (OE)." (PMID 35562740, 2022). "The tumor-promoting properties of POU2F1 OE was partially rescued by LINC01564 knockdown." (PMID 35562740, 2022). "LINC01564 knockdown not only decreased LINC01564 expression, but also inhibited POU2F1 expression in GC tumor induced by POU2F1 overexpression vector." (PMID 35562740, 2022). "AC023310.4, AC091729.1, LINC01564, and MIR3142HG were expressed at higher levels in tumor samples compared to adjacent non-tumor tissues." (PMID 35127708, 2021).
LINC01564 also shares sentences with these, for which no sentence is quoted: colon cancer (3 papers); testicular cancer (3); colorectal cancer (2); metastatic colorectal cancer (2); prostate carcinoma (2); colorectal adenocarcinoma (1); gastric cancer (1); head and neck squamous cell carcinoma (1); inflammatory bowel disease (1); liver cancer (1); lung adenocarcinoma (1); lung squamous cell carcinoma (1); metastatic tumors (1); non-small cell lung carcinoma (1).